DMD (dystrophin)
Diseases named in the same sentence as DMD in open-access papers (continued):
Sharing a sentence is not in itself a finding about the gene and the disease.
Becker muscular dystrophy (continued). "Although the DMD gene encoding dystrophin is more commonly associated with Duchene and Becker muscular dystrophy in both species, other studies have shown somatic DMD variants in human OSA patients." (PMID 36570509, 2022). "This therapeutic category applies to all DMD mutations and potentially to other conditions with shared pathophysiology such as Becker muscular dystrophy or limb-girdle muscular dystrophies." (PMID 34790118, 2021). "Becker muscular dystrophy relates to late-onset and slow progression muscle dystrophy caused by deletions or duplications in the dystrophin gene." (PMID 35070564, 2021). "In-frame mutations generally produce abnormal but partly functional gene product dystrophin, which is part of a protein complex located in the muscle cell membrane, and are associated with Becker muscular dystrophy (BMD)." (PMID 33939732, 2021). "Dystrophinopathy is an X-linked disorder caused by mutations in the DMD gene encoding for dystrophin, with Duchenne and Becker muscular dystrophy being the best known examples." (PMID 34072044, 2021). "DMD is a very large gene (greater than 2 Mb), and its mutations are known to be pathogenic in causing Duchenne and Becker muscular dystrophy." (PMID 34945000, 2021). "Becker Muscular Dystrophy (BMD) is a less severe form of the disease caused by the mutation in the DMD gene and slow progressive with an incidence rate of 1 in 20,000 male children." (PMID 34925456, 2021). "Mutations in the DMD gene encoding the dystrophin protein are responsible for DMD as well as a milder form of the disease referred to as Becker Muscular dystrophy (BMD; OMIM: 300376)." (PMID 32559196, 2020). "Becker muscular dystrophy (BMD) is an X-linked recessive disorder caused by dystrophin gene mutations." (PMID 32961888, 2020). "A milder phenotype of Becker muscular dystrophy (BMD) arises from in-frame mutations in the DMD gene resulting in a production of truncated, partially functional protein." (PMID 32373058, 2020). "The characterisation of mild, or asymptomatic cases of Becker muscular dystrophy arising from the loss of an in-frame dystrophin exon(s) indicates that many of these exons are dispensable." (PMID 33019779, 2020). "By contrast, in-frame dystrophin deletion mutations lead to the related condition Becker muscular dystrophy (BMD), which ranges in phenotype from subclinical to borderline DMD." (PMID 32899151, 2020). "Mutations maintaining the reading frame of the DMD gene are often associated with a milder form of the disease called Becker muscular dystrophy (BMD; Yiu & Kornberg, 2015)." (PMID 32543101, 2020). "Both Duchenne and Becker muscular dystrophies are X-linked progressive neuromuscular disorders caused by loss-of-function mutations in the gene DMD coding for the protein dystrophin." (PMID 32696294, 2020). "By contrast, mutations leading to a partially functioning dystrophin protein are associated with the milder Becker muscular dystrophy (BMD)." (PMID 32899500, 2020). "Becker muscular dystrophy (BMD) is caused by specific mutations in the DMD gene that causes progressive muscle weakness and primarily affects skeletal and cardiac muscle." (PMID 32504006, 2020). "For example, most classically, protein-truncating or frameshift mutations in the DMD gene cause the X-linked Duchenne Muscular Dystrophy; missense mutations or in-frame deletions generally cause the milder Becker Muscular Dystrophy." (PMID 32260281, 2020). "The X-linked DMD gene encodes dystrophin, commonly associated with Duchene and Becker muscular dystrophy in both people and dogs." (PMID 31341965, 2019). "Becker muscular dystrophy exhibits a milder phenotype, having mutations that maintain the reading frame and allow for the production of truncated dystrophin." (PMID 30836656, 2019).
Becker muscular dystrophy (continued). "Sometimes, the ORF is preserved despite the presence of a mutation, which is known as an in-frame mutation, culminating in a truncated yet functional dystrophin leading to a milder form of the disorder, called Becker muscular dystrophy (BMD)." (PMID 29301272, 2018). "Disabling mutations of the dystrophin gene causes DMD, but hypomorphic mutations of dystrophin can cause Becker muscular dystrophy, a similar disorder that manifests over a wide range of severity." (PMID 33072932, 2018). "The dystrophin gene is the one of the largest described in human beings and mutations associated to this gene are responsible for Duchenne or Becker muscular dystrophies." (PMID 27515321, 2016). "Mutations that maintain the translational-reading frame usually lead to internally truncated yet largely functional dystrophin proteins and are associated with typically much milder Becker muscular dystrophy (BMD) phenotypes." (PMID 27588424, 2016). "X-linked dilated cardiomyopathy and dilated cardiomyopathy with mild Becker muscular dystrophy having the DMD mutations." (PMID 26066469, 2015). "We investigated the molecular mechanisms for in-frame skipping of DMD exon 39 caused by the nonsense c.5480T>A mutation in a patient with Becker muscular dystrophy." (PMID 25662218, 2015). "Conversely, the mutations that allow the production of reduced levels of normal or truncated and partially functional dystrophin in muscle are associated with Becker muscular dystrophy (BMD; MIM#300376), a milder allelic variant of DMD." (PMID 25662218, 2015). "We also confirmed a known misregulated splicing event at the 3′ end of the coding region of DMD (dystrophin), a gene in which mutations cause Duchenne and Becker muscular dystrophies." (PMID 25211016, 2014). "Becker muscular dystrophy (BMD) instead is a milder form of dystrophy because it is associated with reduction of wild-type dystrophin or expression of a partially functional protein." (PMID 24084719, 2013). "The milder allelic condition, Becker muscular dystrophy (BMD) is also caused by dystrophin mutations, but these are typically in-frame deletions that allow synthesis of internally truncated dystrophin isoforms that retain partial function." (PMID 24498612, 2013). "Becker muscular dystrophy is a neuromuscular recessive disease related to X chromosome caused by qualitative and quantitative alterations of the dystrophin." (PMID 23365767, 2013). "The most common muscular dystrophies are dystrophinopathies, caused by mutations in the dystrophin gene that depending on the type of mutation, lead to the severe Duchenne or the milder Becker muscular dystrophy." (PMID 24282529, 2013). "As a general rule, most frame-shift mutations in dystrophin lead to DMD whereas internal truncations (in-frame deletions) lead to a milder form of the disease called Becker muscular dystrophy (BMD)." (PMID 20502633, 2010). "Two DCM patients with known genetic syndromes were confirmed to have pathogenic variants, a patient with glycogen storage disease XV had compound heterozygous pathogenic variants in the GYG1 gene, and another had a variant in the DMD gene in a patient with Becker muscular dystrophy." (PMID 39910139, 2025). "At age 13, he was diagnosed Becker muscular dystrophy carrying with the causative mutation in gene DMD (chrX:32,841,413–32,862,977, Hemizygous mutation), and gene testing showed the comorbid mutations of ABCB4(chr7:87041219, heterozygous mutation) and DSC2(chr18:28659938, heterozygous mutation)." (PMID 39044225, 2024). "Dystrophin is well known to be mutated in Duchenne and Becker muscular dystrophies." (PMID 36438562, 2022). "Becker muscular dystrophy belongs to a class of genetically inherited dystrophin deficiencies." (PMID 32138751, 2020).
Becker muscular dystrophy (continued). "Muscle histology as detected by MRI has been found to be the best biomarker of clinical findings in a series of Becker muscular dystrophy patients and to show superior predictive power than patient age, specific gene mutation or dystrophin protein levels in the muscle." (PMID 32592467, 2020). "Becker muscular dystrophy mutations are generally in-frame deletions and provide “templates” for partially functional dystrophin variants that could ameliorate the severe dystrophic muscle phenotype characteristic of DMD." (PMID 31164976, 2019). "Mutations in the DMD gene that preserve the open reading frame allow the production of an abnormal truncated dystrophin still retaining some functional capacity, leading to a milder muscle disease (Becker muscular dystrophy or BMD)." (PMID 29703249, 2018). "The resulting transcript has a restored open reading frame and allows synthesis of a dystrophin protein with a shorter yet functional central rod domain, in many ways similar to the dystrophin protein variants in the typically milder Becker Muscular Dystrophy patients." (PMID 27612288, 2016). "However, isoforms induced by exon skipping, as well as the mini-gene dystrophin constructs envisioned in gene therapy, are also expressed in Becker muscular dystrophy (alleles of dystrophinopathy leading to milder disease)." (PMID 24014378, 2013). "Mutations in dystrophin may result in Duchenne or Becker muscular dystrophy." (PMID 40268053, 2025). "A related, milder disease—Becker muscular dystrophy (BMD)—is caused by mutations that preserve the open reading frame, producing a partially functional dystrophin protein." (PMID 40724990, 2025). "Becker muscular dystrophy (BMD) is an X-linked genetic disorder caused by mutations in the dystrophin gene, leading to progressive muscular weakness." (PMID 40909422, 2025). "DMD and Becker muscular dystrophy (BMD) are both characterized by a loss of dystrophin expression, with total loss in DMD and partial loss in BMD." (PMID 39857686, 2025). "Becker muscular dystrophy (BMD) is a rare and heterogeneous form of dystrophinopathy caused by expression of altered dystrophin proteins, as a consequence of in-frame genetic mutations." (PMID 40483507, 2025). "Becker muscular dystrophy (BMD) is an X-linked recessive inherited disorder characterized by slowly progressing muscle weakness of the legs and pelvis, caused by mutations in the DMD gene, which encodes dystrophin protein." (PMID 39659883, 2024). "While DMD is typically associated with almost complete loss of dystrophin expression, Becker muscular dystrophy (BMD) is an allelic disorder caused by hypomorphic mutations associated with some residual dystrophin expression and a milder phenotype." (PMID 38669554, 2024). "Specific in-frame variants in the DMD gene cause Becker muscular dystrophy (BMD) (OMIM 300376), which has a later onset and a milder and varied clinical course." (PMID 39117454, 2024). "Becker muscular dystrophy (BMD) is an X-linked recessive disorder caused by dystrophin in-frame deletion in the DMD gene." (PMID 39840281, 2024). "In frame deletions lead to a shorter but partially functional dystrophin, associated with milder Becker Muscular Dystrophy (BMD)." (PMID 38438561, 2024). "Becker muscular dystrophy (BMD) is a milder form of DMD typically caused by in-frame mutations of the dystrophin gene." (PMID 38495661, 2024). "Mutations in DMD can also cause Becker muscular dystrophy (BMD), a milder disease characterized by the preserved production of a partially functional dystrophin." (PMID 38891777, 2024). "Becker muscular dystrophy (BMD) is an X-linked recessive neuromuscular disorder caused by a mutation in the dystrophin gene." (PMID 39640169, 2024). "Mutations in the DMD gene can cause Duchenne or Becker muscular dystrophy (DMD/BMD) by affecting the giant isoform of dystrophin, a protein encoded by the DMD gene." (PMID 37374149, 2023).
Becker muscular dystrophy (continued). "Becker muscular dystrophy (BMD), a less severe dystrophinopathy with later onset and slower rate of progression, is typically caused by variants in the DMD gene that preserve the open reading frame." (PMID 37350320, 2023). "Becker muscular dystrophy (BMD) is a mild degenerative disease caused by mutations of the DMD gene, in which the restored open reading frame produces truncated partially functional dystrophin protein." (PMID 38203473, 2023). "Mutations in DMD can also cause Becker muscular dystrophy (BMD), which is characterized by a milder phenotype than DMD, but BMD mutations generally maintain the reading frame of DMD." (PMID 37667454, 2023). "A milder form of muscular dystrophy that is also linked to mutations in the dystrophin gene is known as Becker muscular dystrophy (BMD; MIM #300376)." (PMID 37834310, 2023). "This dystrophin is found in Becker muscular dystrophy (BMD), which is milder than DMD and is associated with a later onset of symptoms and slower disease progression in BMD." (PMID 35886024, 2022). "In comparison, Becker muscular dystrophy (BMD) is a milder neuromuscular disease caused by mutations in the DMD gene that maintains the open reading frame, producing internally deleted but partially functional dystrophin proteins." (PMID 36556333, 2022). "Dystrophin with partial function can be produced when variants in DMD maintain the open reading frame, leading to Becker muscular dystrophy (BMD), which has milder clinical symptoms." (PMID 36365206, 2022). "Becker muscular dystrophy (BMD) is a neuromuscular disorder due to in‐frame mutations in the DMD gene, located on the X chromosome." (PMID 35880500, 2022). "Becker muscular dystrophy (BMD) is an X‐linked neuromuscular disorder due to mutation in the DMD gene, encoding dystrophin." (PMID 35880500, 2022). "Duchenne/Becker muscular dystrophy (DMD/BMD) is an X-linked hereditary neuromuscular disorder caused by mutations in the dystrophin gene." (PMID 36361501, 2022). "Mutations in DMD that maintain the reading frame result in a milder phenotypic form of the disease, Becker muscular dystrophy (BMD)." (PMID 33407808, 2021). "On the other hand, ‘In-frame’ mutations perverse the frame of DMD gene and generate partial functional dystrophin protein, which lead to less severe Becker muscular dystrophy (BMD) phenotype." (PMID 34490244, 2021). "Often, in Becker muscular dystrophy (BMD), which is the mild allelic form with in-frame mutations of the dystrophin gene, LOA occurs after the age of 16." (PMID 33910603, 2021). "Interestingly, there have been two reported case studies of young boys with Hodgkin’s disease and non-Hodgkin’s lymphoma (a large B-cell lymphoma of the ascending colon) associated with Becker muscular dystrophy, the milder allelic form of DMD caused by in-frame DMD deletions." (PMID 33188621, 2021). "A milder form of DMD exists, called Becker muscular dystrophy (BMD), which is typically caused by in-frame dystrophin gene mutations." (PMID 32650403, 2020). "Becker muscular dystrophy (BMD), a related dystrophinopathy, is characterized by a later onset and slower disease progression and is principally caused by in‐frame dystrophin mutations." (PMID 31849191, 2020). "In-frame mutations in DMD cause a milder form of X-linked muscular dystrophy, called Becker muscular dystrophy (BMD), characterized by the reduced expression of truncated dystrophin." (PMID 32859695, 2020). "Becker muscular dystrophy (BMD) is a milder disorder, characterized instead mostly by in-frame mutations in the DMD gene." (PMID 32650403, 2020). "Most cases of DMD are caused by frameshift-generating deletions of one or more exons of the DMD gene, whereas mutations that preserve the reading frame are the cause of a milder form of the disease known as Becker muscular dystrophy (BMD)." (PMID 31028078, 2019).
Becker muscular dystrophy (continued). "Conversely, mutations that still allow for a truncated dystrophin to be produced and trafficked to the sarcolemma result in the overall milder Becker muscular dystrophy (BMD)." (PMID 31443395, 2019). "Duchenne and Becker muscular dystrophy (DMD/BMD) are X-linked muscle disorders caused by mutations of the DMD gene, which encodes the subsarcolemmal protein dystrophin." (PMID 30836656, 2019). "DMD mutations can also cause a less severe dystrophinopathy known as Becker muscular dystrophy (BMD), which has an incidence ranging from 5.8 to 7.2 in 100,000 live male births." (PMID 30544634, 2018). "A related but milder form of the disease called Becker Muscular Dystrophy (BMD) is caused by in-frame mutations in the DMD gene that allow expression of an internally truncated but partially functional protein." (PMID 28742140, 2017). "Becker muscular dystrophy (BMD) is a progressive neuromuscular disorder caused by mutations in the dystrophin gene." (PMID 29457107, 2017). "Exonic deletion mutations in the dystrophin gene cause not only DMD but also Becker muscular dystrophy (BMD), a milder progressive muscle-wasting disease." (PMID 28208626, 2017). "Becker muscular dystrophy (BMD) has milder symptoms than DMD and is mostly caused by in-frame deletions in the DMD gene, which is able to express an internally truncated, but partially functional, protein." (PMID 27754374, 2016). "Duchenne and Becker muscular dystrophy (DMD and BMD) are X-chromosomal recessive neuromuscular disorders that are caused by mutations in the dystrophin gene and characterized by cardiac involvement." (PMID 27150296, 2016). "A milder allelic form, Becker muscular dystrophy (BMD) is usually caused by in-frame mutations in the dystrophin gene, resulting in the synthesis of reduced levels of a possibly partially functional dystrophin." (PMID 26974331, 2016). "Duchenne and Becker muscular dystrophy (DMD and BMD) are X-chromosomal recessive neuromuscular disorders that are caused by mutations in the dystrophin gene that subsequently lead to either total absence or structural impairment of the dystrophin protein." (PMID 27150296, 2016). "Duchenne and Becker muscular dystrophy (DMD and BMD) are X-linked recessive muscle-wasting diseases arising from mutations in the massive dystrophin gene (DMD) that leads to degeneration of muscle." (PMID 26745801, 2016). "There are also mutations that maintain the open reading frame (ORF) of the DMD gene leading to a milder form of dystrophy called Becker Muscular Dystrophy (BMD)." (PMID 27515321, 2016). "Likewise, a patient with a pathogenic variant in DMD should be carefully examined and monitored for other symptoms of Becker muscular dystrophy as additional symptoms may be subtle or may appear with a later onset." (PMID 27446933, 2016). "In-frame deletions within the Dystrophin sequence can result in a shortened but partially functional protein that causes Becker muscular dystrophy (BMD)." (PMID 26459831, 2015). "DMD and the milder, allelic Becker muscular dystrophy (BMD) represent a spectrum of disorders that stem from a loss of functional dystrophin protein." (PMID 23939629, 2013). "Becker muscular dystrophy (BMD) is a condition due to mutations in the gene that expresses the dystrophin protein, located in X chromosome." (PMID 23365767, 2013). "This prediction is further supported by the majority of patients with Becker muscular dystrophy (BMD), who have dystrophin mutations that cause a milder skeletal muscle disease, and typically progress to heart failure." (PMID 21586145, 2011). "Although Duchenne and Becker Muscular Dystrophies are directly related to the dystrophin protein, it is very important to find other proteins that contribute to the clinical heterogeneity among patients with this disease." (PMID 39865125, 2025).